LEP (leptin)
Diseases named in the same sentence as LEP in open-access papers (continued):
Sharing a sentence is not in itself a finding about the gene and the disease.
Obesity (continued). "Therefore, in obesity, the failure in leptin action may lead to a reduction of energy expenditure and contributes to weight gain; at the same time, a compensatory hyperleptinemia may favor the development of hypertension and lead to overt cardiovascular disease." (PMID 34068919, 2021). "Therefore, it might be hypothesized that the described anorexigenic feedback mechanism associated with BDNF signaling is attenuated in patients suffering from obesity, comparable with the insulin or leptin resistance as a consequence of long-lasting overeating in patients suffering from obesity." (PMID 33367955, 2021). "A mother with excessive weight gain or obesity has a suboptimal uterine nutritional climate, which may disrupt the inflammatory and hormone metabolic homeostasis of the mother, including insulin resistance, increased level of leptin, lipid, and pro-inflammatory cytokines." (PMID 34513768, 2021). "It decreases body weight by suppressing appetite and promoting energy expenditure in physiologic conditions, but hyperleptinemia is observed in patients with obesity and T2DM due to leptin resistance." (PMID 34501456, 2021). "Adipocytes produce and secrete the adipocytokines tumor necrosis factor-alpha (TNF-a), interleukin (IL)-6, and leptin (LEP), the levels of which are directly related to the degree of obesity." (PMID 34944525, 2021). "However, in our study, we only determined the weights of rats before the experiment, and thus, it was difficult to ascertain whether the hyperandrogenic PCOS rats were obese and difficult to analyze whether obesity was related to inflammation and leptin resistance." (PMID 34422044, 2021). "In excessive lipid-loaded condition or obesity, elevated circulating level of TNF-α leads to increased production of leptin." (PMID 34421909, 2021). "Acupuncture significantly downregulated the serum levels of CRP, TG, CHO, LDL, leptin, and prostaglandin E and upregulated the serum levels of HDL in rats with simple obesity." (PMID 34646336, 2021). "The genes that formed the negative regulation of the glucose import category (PEA15, SIRT6, LEP, and VIMP), were related to obesity and diabetes in human." (PMID 33850161, 2021). "Mutation of the STAT3-recruiting tyrosine 1138 on the LepRb prevented SOCS3 feedback inhibition of leptin signalling, while overexpression of a constitutively active version of STAT3 in POMC neurons elevated Socs3 expression and led to obesity." (PMID 34502119, 2021). "Obesity and OSAS can lead to elevated levels of the adipose-derived hormone leptin, which increases metabolism." (PMID 34671315, 2021). "In the present study, both immunohistochemistry and RT-PCR experiments demonstrated an increase in visceral adipose tissue content of leptin, iNOS and TNF-α in the diet induced obesity group." (PMID 33761942, 2021). "More interestingly, studies have shown that inhibiting the NF-κB cascade in microglia reduces microgliosis and diet-induced weight gain and restores hypothalamic leptin sensitivity, suggesting a promising therapeutic target for HFD-induced obesity." (PMID 34275474, 2021). "Obesity is a conspicuous trait of the Ossabaw pig and heterozygosity of POMC, LEP and LEPR genes were reported to impact the obesity of humans and mice." (PMID 34585119, 2021). "The proportion of participants with Leptin and CRP levels in the fourth quartile was highest among those with obesity." (PMID 33680494, 2021). "For example, in 97 patients with obesity underwent either RYGB or biliopancreatic diversion with duodenal switch, decreased levels of IFN-γ, hs-CRP, TNF-α, IL-13, IL-6, IL-1ra, C3, and leptin were described compared with baseline levels at 1-year follow-up55." (PMID 34108550, 2021).
Obesity (continued). "The presence of allele G was found to be associated with body mass index (BMI) and serum leptin, regardless of ethnicity or sex, even though recent advances reported that obesity status and female sex might exert modifying effects on polymorphism-related leptin concentrations." (PMID 34208585, 2021). "Other critical modulators of the obesity phenotype exist within the ATP2A1 locus, such as SH2B1, a gene involved in leptin and insulin signaling." (PMID 34489471, 2021). "Although these experiments initially suggested that high circulating leptin levels may protect cartilage degeneration in short-term periods, the response of human chondrocytes to continuous exposures of leptin, as occurs in obesity, showed a reduction in cell viability." (PMID 33673730, 2021). "Some rare diseases such as monogenic obesity due to leptin-melanocortin pathway anomaly have also been of special interest as understanding this specific pathway might lead to therapeutic innovations or etiologic insights in other, more common, forms of obesity." (PMID 33743790, 2021). "In specific, hyperleptinemia, commonly observed in obesity, was positively correlated to PTH in both adult and pediatric individuals, indicating that stimulation of leptin—PTH axis is the initial source of hyperparathyroidism." (PMID 34422722, 2021). "Other researchers also found that due to obesity in PCOS patients, the increased circulating leptin (LP) levels within the body led to leptin resistance, which can also significantly promote chronic low-grade inflammation." (PMID 34422044, 2021). "In accordance with the pleiotropic actions of leptin, emerging studies have evaluated the efficacy of leptin-based and LEPR antagonist therapy as anti-obesity approaches in the setting of both leptin sensitivity and resistance states." (PMID 34208585, 2021). "Therefore, the imbalance in leptin levels, caused by maternal LPD, suggests that these alterations could not prepare the individual for an environment with an excess of food, leading to an increased risk of obesity." (PMID 35052371, 2021). "Furthermore, studies have shown that gastric leptin secretion also responds to the intake of certain macronutrients, thereby activating mechanisms that may lead to peripheral LR and be critical early points in the pathophysiology of obesity." (PMID 34899599, 2021). "Obesity is regarded as a state of low-grade systemic inflammation, where high levels of tumour necrosis factor-α (TNF-α), interlukin-6 (IL-6) and leptin have been observed in obese compared to normal adipocytes." (PMID 34616553, 2021). "The post hoc analysis adjusted for confounders including body composition and physical inactivity reduced the significance of leptin and FABPA, supporting a role for obesity in frailty progression." (PMID 34252094, 2021). "According to existing research conclusions, HIF regulates leptin through suppressor of leptin signaling (SOCS), one of the hypothalamic signaling molecules/pathways that have been extensively studied to inhibit obesity-induced leptin resistance." (PMID 33763034, 2021). "For example, both obesity and IUGR exhibit similar levels of leptin and insulin resistance in response to their prenatal nutritional status and postnatal accelerated weight gain." (PMID 34211985, 2021). "A few studies have examined blocking negative regulators of the leptin signaling pathway, including SOCS3 and PTP1B, to enhance leptin administration effects in individuals with obesity." (PMID 34084149, 2021). "Tanycytes also play a key role in our obesity and T2DM models in this review (DIO Western, db/db and BTBR ob/ob) as they sense leptin and glucose." (PMID 34063911, 2021). "A bidirectional relationship might exist between obesity-related traits and MDD with atypical features, as a large international consortium study showed that patients with atypical depression carried a higher number of genetic risk variants for disturbances in BMI, CRP and leptin." (PMID 33653423, 2021).
Obesity (continued). "Experimental data are limited regarding the status of leptin during the progression of ALS, even though this hormone is historically known for its important role in regulating body weight, and mild obesity appears to improve survival in ALS patients." (PMID 34638645, 2021). "In line with the alterations detected in the redox homeostasis, increased plasma inflammation was also observed, in the children with obesity, in particular CRP and leptin levels." (PMID 34457110, 2021). "They found that both the expression level of leptin and resistin were significantly increased in the HFD group treated with DOX, confirming obesity conditions induced the changes in tissue fatty acid composition to further reduce the therapeutic effect of DOX." (PMID 34350120, 2021). "To further elucidate the correlation between obesity and CD146 expression, we examined CD146 expression in adipose tissue from high‐fat diet‐induced and leptin deletion‐induced obese mice (ob/ob mice)." (PMID 33747748, 2021). "For example, epinephrine can enhance the leptin transportation across the BBB, whereas lipopolysaccharide, obesity, triglycerides, and fasting largely reduce the rate of transport." (PMID 33849593, 2021). "In contrast, neuron-specific PTP1B KO mice were protected from diet-induced obesity and glucose intolerance, indicating that neuronal PTP1B regulates body weight, adiposity, and leptin signaling." (PMID 34726241, 2021). "The serum levels of adipokines, leptin and resistin, were increased by the consumption of HFD as the mice developed obesity." (PMID 33535476, 2021). "Leptin coincided with the inflammatory cytokines in aPAVT, whereas UCP-1 was elevated in tPVAT but suppressed in aPVAT throughout diet-induced obesity." (PMID 34239444, 2021). "Finally, the elevated insulin and leptin levels in children with obesity might promote growth." (PMID 34386750, 2021). "STAT3 is the main signaling factor of IL-6, and obesity has been shown to chronically activate intracellular JAK-STAT3 signaling through increased levels of IL-6 and leptin." (PMID 35087513, 2021). "This study suggests that PNE has a potent anti-obesity effect, inhibiting lipogenesis in WAT, even though HFD-induced leptin resistance-mediated disruption of POMC neuronal activity." (PMID 33919440, 2021). "In cultured human SCs, the physiological concentration of leptin (5 ng/mL) upregulates glucose transporter 2 proteins (GLUT-2) levels, whereas obesity levels of leptin (25–50 ng/mL) decreased acetate production from glucose in a dose dependent-manner." (PMID 34940598, 2021). "Induction of hypothalamic ER stress leads to increased food intake, reduced energy expenditure and resultant obesity, and this is mediated at least in part by defective α-MSH production among POMC neurons and development of leptin resistance." (PMID 34122343, 2021). "However, in diet-induced obesity characterized by leptin resistance, mice do display hypertension, which was shown to be blunted by antagonism of ObR in a selective area of the hypothalamus, the dorsomedial nucleus, thus suggesting that this area is spared from leptin resistance." (PMID 34512392, 2021). "For this purpose, we analyzed the anorexigenic response to leptin and the hypothalamic insulin signaling after two weeks of HFD, before the onset of obesity." (PMID 34015524, 2021). "As a result of the experiment, it was confirmed that leptin was increased in all obesity-induction groups compared to the NFD group, and leptin levels were decreased in the Gar- and BSE-treated groups compared to the HFD group." (PMID 34564426, 2021). "The mean concentrations for leptin and CRP were higher in participants with overweight/obesity compared to participants who were underweight/normal weight (7.9 ± 5.9 ng/ml vs. 3.5 ± 4.7 ng/ml and 0.33 ± 0.6 μg/ml vs. 0.14 ± 0.4 μg/ml, respectively)." (PMID 33680494, 2021).
Obesity (continued). "Therefore, it would be reasonable to posit that while leptin may elicit a therapeutic response at physiologically relevant concentrations, this beneficial effect of leptin is completely abrogated in diseased states such as obesity and diabetes, characterized by hyperleptinemia." (PMID 34064112, 2021). "Among those genes are insulin receptors, fatty acid synthase, lipoprotein lipase, adiponectin, leptin, acetyl-CoA carboxylase beta, and fatty acid binding protein 4 (FABP4), the latter being a new player connecting obesity with breast cancer development." (PMID 33801973, 2021). "Moreover, preclinical studies focusing on the role of the gut microenvironment have shown that gut-derived endocrine factors may reduce microglial activation and hypothalamic inflammatory processes and amplify the catabolic actions of exogenous leptin in obesity." (PMID 33741533, 2021). "In general, regular exercise decreases the secretion of pro-inflammatory mediators from AT and SKM, such as TNFα, leptin, and MCP-1, and improves LGI status in obesity." (PMID 33670492, 2021). "Moreover, the observation that obese individuals exhibit changes in appetite and energy expenditure after moderate weight loss and that these changes are blunted by the administration of leptin, suggests that the high leptin concentrations in obesity may be biologically relevant." (PMID 33804765, 2021). "Serum leptin, insulin, and HOMA-IR were significantly elevated in with obesity compared to normal-weight groups during childhood." (PMID 34386750, 2021). "Using this algorithm, all hug targets of metformin against obesity-related hypertension were identified accordingly, including IL6, CCL2, Leptin (LEP), Apolipoprotein B (APOB), serine protease inhibitor clade E member 1 (SERPINE1), Apolipoprotein E (APOE)." (PMID 34334083, 2021). "Some previous studies suggested that leptin was considered likely to be the important signal between obesity and puberty, and GTP has been found to suppress the effects of leptin or inhibit the expression of leptin in adipose tissue in obese rats and adults." (PMID 34712203, 2021). "As results, the identified findings using network pharmacology analysis had identified total six hug genes of metformin treating obesity/hypertension, including IL6, CCL2, LEP, APOB, SERPINE1, and APOE." (PMID 34334083, 2021). "Long-lasting excessive caloric intake and increased weight gain change the adaptive abilities of the HPT axis, and in obesity, leptin resistance appears primarily at the ARC level, but the direct effect of leptin on the PVN remains unchanged." (PMID 34574358, 2021). "Therefore, the crucial question is whether or not the cytokine storm in COVID-19 patients with obesity is linked to leptin dysregulation." (PMID 34220807, 2021). "Diet-induced obesity (DIO) interferes with the hormonal regulation of body weight and hunger, as leptin resistance and hyperleptinemia frequently co-exist." (PMID 34899599, 2021). "Therefore, PAI-1 inhibitors may act as leptin sensitizers in states of HFD-induced obesity." (PMID 32670063, 2020). "However, sustained leptin resistance could lead to obesity, cancer and autoimmune diseases." (PMID 32824322, 2020). "Further links between immune cells, obesity and MAPK have been demonstrated through examining the effects of leptin in T helper immune cells, albeit in allergic airways disease." (PMID 32069845, 2020). "Molecular markers of obesity (e.g. IL-6, CRP, leptin, interleukin 1 beta [IL-1β]) increase the generation of myeloid-derived suppressor cells (MDSCs)." (PMID 33123173, 2020). "Consistent with the polarization toward the Th2/Th17 lineages, leptin and inflammatory cytokine expressions in plasma, PLF, and adipose tissues were upregulated with the concurrence of obesity and sepsis." (PMID 33223959, 2020). "Strikingly, ATZ prevented the increase in blood pressure and the HFD-induced obesity as observed by lower body weight, WAT index, triglycerides, NEFA, and leptin in plasma." (PMID 32351670, 2020).
Obesity (continued). "In this study, the levels of Leptin mRNA and plasma leptin were increased in the HFD groups, but Adipoq mRNA levels, which are widely known to be downregulated under conditions of obesity, were unchanged." (PMID 31965758, 2020). "As expected, markers of adiposity (BMI, BF, or leptin) and lipolysis [circulating free fatty acids (FFA) and glycerol] were increased (p < 0.01) in both groups of patients with obesity compared to those of the lean individuals." (PMID 32512939, 2020). "A more favorable adipokine profile, characterized by decreased osteonectin, leptin, and RBP-4 and increased adiponectin levels was shown in MHO children with respect to metabolically unhealthy children suffering from obesity." (PMID 33192583, 2020). "Excess leptin can result in abnormal OBR signaling, leading to disease progression and poor prognosis in human obesity-related cancers." (PMID 32471192, 2020). "We found a significantly higher median concentration of leptin and FGF 21 in patients from group A with diabetes and obesity, compared to patients from group B with the same metabolic diseases." (PMID 32570721, 2020). "Even so, in obesity, chronic activation of JAK-STAT3 leads to leptin and insulin resistance in the central nervous system and peripheral organs, respectively." (PMID 32752277, 2020). "In the state of obesity, increased CETP levels are correlated with leptin levels, in line with the fact that adipose tissue is one of the major sources of CETP expression." (PMID 33256096, 2020). "In serum and synovial fluid, eight obesity-induced inflammatory cytokines (VEGF, MIP-1α, MIP-2, IP-10, IL-1α, TNF-α, MCP-1, and leptin) and LPS were increased in the DIO-KOA group compared with the control group." (PMID 32724821, 2020). "Indeed, obesity-related pathological consequences, such as insulin and leptin resistance, mitochondrial dysfunction and ROS production, may anticipate and accelerate the physiological aging processes that involve also higher susceptibility to neurodegenerative diseases." (PMID 32825115, 2020). "We also found that the administration of phloretin significantly inhibited the serum levels of leptin, glucose, and insulin and increased serum adiponectin levels compared to mice with HFD-induced obesity." (PMID 33014333, 2020). "While leptin has not been successful in treating obesity as a weight loss drug, it is possible that targeting leptin or leptin signaling could be therapeutic for autoimmune disease or the low-grade, chronic inflammation associated with obesity and metabolic syndrome." (PMID 33584724, 2020). "The expression levels of other eight obesity-related genes (TMEM18, KCTD15, GNPDA2, SH2B1, FTO, LEP, PCSK1, and GPR120) in about half types of cancer tissues were higher/lower than those in the corresponding normal tissues." (PMID 33299884, 2020). "Recent data show that the adipokine leptin can modulate Notch/RBP-Jk signaling, thereby linking the obesity pandemic with cancer and chemoresistance." (PMID 32471192, 2020). "Therefore, novel therapies incorporating effective natural agents (macro and micronutrients), particularly agents with the dual properties of preventing inflammation and controlling body weight by improving leptin sensitivity, might be an alternative intervention targeting obesity and GDM." (PMID 32630697, 2020). "Long term intake of high protein diet in obesity-prone rats reduced food intake and WAT mass while improving basal blood sugar, insulin levels, leptin, and triglyceride levels in addition to glucose tolerance." (PMID 33282920, 2020). "We studied the effects of Ramadan intermittent fasting (RIF) on gut hormones (leptin, glucagon-like peptide-1 (GLP-1), peptide YY (PYY), cholecystokinin (CCK), and ghrelin) in males with obesity." (PMID 32756479, 2020).